TNF (tumor necrosis factor)
Diseases named in the same sentence as TNF in open-access papers (continued):
Sharing a sentence is not in itself a finding about the gene and the disease.
liver fibrosis (continued). "SolB reverses hepatic fibrosis by inhibiting hepatocyte injury, and WeD could block the production of TNF-α and IL-1β in macrophages and the activation of TGF-β1/Smad signaling pathway in activated HSCs." (PMID 34149411, 2021). "TNF-α can promote the survival of activated HSCs and promote the development of liver fibrosis." (PMID 33790974, 2021). "Therefore, the inhibition of TNFα signalling can exert therapeutic effects on liver fibrosis itself at later stage." (PMID 33414474, 2021). "Finally, in order to explore the role of WEPE in the inflammatory response of liver fibrosis, we evaluated the levels of TNF-α, IL-1β, and IL-6 in the rat serum." (PMID 34712342, 2021). "In addition, liposomal (SPB) hydroalcoholic extract treatment decreased the liver expression of inflammatory cytokines (IL-1β, TNF-α) and liver fibrosis markers (TGF-β and SM-α)." (PMID 34707781, 2021). "Adopting the TGF-β1 inhibitor pirfenidone, TNF-α inhibitor pentoxifylline, and monocytes depressor clodronate-loaded liposomes, we demonstrated that inhibition of inflammatory action ameliorated HSCs activation and liver fibrosis." (PMID 33980818, 2021). "Moreover, expression of proinflammatory cytokines (IL-1β and TNF-α) and liver fibrosis markers (TGF-β and SM-α) which are driving forces of many liver disorders was also determined." (PMID 34707781, 2021). "Hepatic macrophages also enhance liver fibrosis through the release of IL-1β, TNF-α, CCL2 and PDGF." (PMID 34805276, 2021). "Moreover, administration of IL-22 inhibits HSC activation, reduces the production of pro-inflammatory factors (IL-1β, IL-6, and TNF-α), and ameliorates liver fibrosis in CCl4-induced liver fibrosis." (PMID 33869241, 2021). "In the in vivo model, infusion of the miR-150 secretome into mice with liver fibrosis abrogated the increase in serum levels of systemic inflammatory cytokines, such as IL-6 and TNF-α, and induced increased expression of antifibrotic, proliferation, and antioxidant activity markers in the liver." (PMID 32152450, 2020). "DOP reduced LPS entry into the liver to activate the TLR4/NF-κB signaling pathway, thereby reducing the production of inflammatory factors such as TGF-β and TNF-α, increasing the production of anti-inflammatory factors such as IL-10, and reducing the deposition of collagen to treat liver fibrosis." (PMID 32226380, 2020). "LCZ696 was superior to valsartan in reducing AST, hepatic fibrosis, tissue IL-1β, TNF-α and NF-κB." (PMID 33173431, 2020). "The expanded amount of TNF-α-producing macrophages and IL-17-producing γδ T cells, which have been shown to promote hepatic fibrosis progression, may act as a feedback mechanism responding to TCR deficiency, thereby assuring aggravated hepatic fibrogenesis." (PMID 33391261, 2020). "Expression of IL-6, IL-1β, and TNF-α was also decreased in the acute hepatic fibrosis model." (PMID 33262757, 2020). "Similarly, knock down of Jun N-terminal kinase 12 (JNK-1/2) from KCs reversed liver fibrosis in a choline-deficient L-aminoacid-defined (CDAA) model, with a decline in inflammatory responses, including TNF-α, IL6, IL-1β, and TGF-β." (PMID 32612603, 2020). "Indeed, knockout of TREM-1 (Triggering receptor expressed on myeloid cells), which is highly expressed on KCs in liver fibrosis, reduced liver fibrosis through the inhibition of TNF-α and IL-6 responses in a number of chronic injury models." (PMID 32612603, 2020). "Therefore, the role of TNF-α in the progression of liver fibrosis should be determined more carefully." (PMID 31847135, 2019). "Altogether, it is likely that both IL-1 and TNF-α are both required to successfully translate inflammation into fibrosis; however, increased IL-1 signaling by itself may contribute to an increase in liver fibrosis." (PMID 30875826, 2019). "TNF-α-driven inflammatory reaction plays a crucial role in the initiation of liver fibrosis." (PMID 31847135, 2019).
liver fibrosis (continued). "Indeed, analysis of transcriptomics data from the HDAC5-transduced UC cell lines by IPA highlighted parallels between the effects of HDAC5, hepatic fibrosis, TGFβ and TNFα signaling." (PMID 31052182, 2019). "In addition, acute binge drinking has been shown to significantly increase serum bacterial DNA and pro-inflammatory cytokines such as IL-6, TNF-α, and IL-1β to indirectly contribute to liver fibrosis." (PMID 31717860, 2019). "Growth factors and cytokines within the secretome such as transforming growth factor beta isoform 3 (TGF-β3), hepatocyte growth factor (HGF), IL-10, and tumor necrosis factor-alpha (TNF-α) can modulate cell signaling and processes involved in fibrogenesis and can attenuate liver fibrosis." (PMID 31270691, 2019). "We thus believe that blocking TNF-α-driven inflammation at the appropriate stage of liver fibrosis could be an efficient strategy to prevent fibrosis." (PMID 31847135, 2019). "M1 secretes IL‐1 and TNF‐α which can weaken hepatic fibrosis by inducing HSCs apoptosis." (PMID 31724278, 2019). "In conclusion, irritative factors such as CCl4 injection stimulate the proliferation of M1 macrophages, which further trigger HSC activation into α-SMA-positive myofibroblasts to accelerate the development of liver fibrosis by expressing TNF-α, IFN-γ, and IL-6." (PMID 30635047, 2019). "Moreover, the levels of TNF-α, MDA, NO, and ONOO- in the lung homogenate were significantly increased, suggesting that the liver fibrosis would cause the pathological changes in the lung tissue, mainly the inflammatory responses." (PMID 33817199, 2019). "Moreover, expression of Th1 or Th2 cytokines important for liver fibrosis, such as IL-6, IL-10, IL-13, and TNF-α, were also detected in our experiment." (PMID 29703259, 2018). "TNF-α can induce the activation of HSCs, leading to liver fibrosis in rats." (PMID 28594374, 2017). "TNF-α is a pro-inflammatory cytokine and an inducer of hepatic fibrosis." (PMID 29050312, 2017). "In conclusion, our findings demonstrated that HCV infection triggers a local and systemic cytokine ensemble orchestrated by TNF and tuned by IL-10 in such a manner that mirrors the liver fibrosis score, which highly suggests the relevance of these set of biomarkers for clinical investigations." (PMID 26742960, 2016). "Neutralization of IL-9 further suppressed expression of inflammatory cytokines including IL-9, IL-17A, IFN-γ, TGF-β1, IL-6, IL-4 and TNF-α in the mouse model of hepatic fibrosis, suggesting IL-9 may regulate the inflammatory responses to liver fibrosis." (PMID 26728971, 2016). "Collectively, this is the first report indicating that GA induces TNF signaling–triggered necroptosis in aHSCs, which may offer an alternative strategy for the amelioration of liver fibrosis." (PMID 25816210, 2015). "BBG also ameliorated liver fibrosis and down-regulated hepatic interleukin-6 (IL-6), tumor necrosis factor-alpha (TNF-α), PDGF, IL-1β, transforming growth factor-beta (TGF-β), p-extracellular-signal-regulated kinases (ERK), and alpha-smooth muscle actin (α-SMA) expressions in CBDL rats." (PMID 25933224, 2015). "Elevated levels of TNF-α, IL-6, and IL-1 β were also previously reported in liver fibrosis in rats." (PMID 25945106, 2015). "In experimental studies TNF-α seems to be essential to liver fibrosis development." (PMID 24757288, 2014). "Thus in a mouse model of liver fibrosis, hepatic CD11c+ DCs expand 5-fold, inducing TNF-α, MCP-1 and IL-6 expression in co-cultured NK cells, with effects on inflammation, cell proliferation as well as fibrotic response." (PMID 24516640, 2014). "Studies have shown that ALD associated miRNAs play a crucial role in the regulation of liver-inflammatory agents such as tumour necrosis factor-alpha (TNF-α), one of the key inflammatory agents responsible for liver fibrosis (liver scarring) and the critical contributor of alcoholic liver disease." (PMID 24400890, 2014).
liver fibrosis (continued). "Besides the progressive hepatic fibrosis, NEMOΔhepa livers also comprise a strong and persistent inflammation, which is among others – characterised by constantly activated TNF-α." (PMID 24979756, 2014). "Prior studies have explored the efficacy of anti-TNF-α treatments to reduce hepatic fibrosis, with some experimental evidence suggesting that inhibition of TNF-α signaling during liver injury may be efficacious." (PMID 25152891, 2014). "Liver fibrosis is influenced by tumor necrosis factor alpha (TNF-α) and interleukin 10 (IL-10)." (PMID 25013899, 2014). "In conclusion, a GG genotype at -238 position in the TNF-α promoter gene influences the risk of liver cirrhosis in HIV-HCV infected patients, even more than those classically accepted factors influencing the progression of liver fibrosis." (PMID 23840511, 2013). "TNF-α deficiency reduced liver fibrosis without affecting liver injury, inflammatory cell infiltration, and liver regeneration after CBDL+CDL." (PMID 23755201, 2013). "Thus, the roles of TNF-α on HSCs activation and liver fibrosis are complicated and remain controversial." (PMID 23755201, 2013). "In the case of liver fibrosis, it has been suggested that KCs produce a variety of proinflammatory cytokines, such as tumor necrosis factor (TNF)-α, interleukin (IL)-1β, and macrophage inflammatory protein (MIP)-1, which provoke HSC activation and subsequently contribute to hepatic injury." (PMID 22531084, 2012). "In accord, our work in experimental steatohepatitis and hepatic fibrosis reveals an up-regulation of the TGFβ signaling pathway and proinflammatory cytokine expression (i.e. IL-1β, IL-6, and TNFα) in mice lacking CNP; moreover, many of these pathogenic processes can be reversed by CNP treatment." (PMID 39816244, 2025). "Thus, TNF-α takes an important role in the progression and perpetuation of liver fibrosis." (PMID 40607400, 2025). "Moreover, oxidative stress can increase the levels of IL-2, TNF, and IL-2, which may contribute to hepatic fibrosis." (PMID 39555193, 2024). "Similarly, our results showed that TFPCP could ameliorate the inflammatory response (TNF-α, Il-6 and IL-1β) in a CCl4-induced liver fibrosis rat model." (PMID 38074148, 2023). "We have previously shown that Notch blockade in macrophages could impair the expression of inflammatory factors interleukin-1 beta (IL1β) and tumor necrosis factor alpha (TNFα) by up-regulation of cylindromatosis (Cyld), and then ameliorate hepatic fibrosis in mice." (PMID 37063432, 2023). "Importantly, VSC-CDs demonstrated a mitigating effect on CCl4-induced liver fibrosis, as evidenced by the reduction in inflammatory cytokines (TNF-α, IL-6, IL-1β), elevation in antioxidant levels (SOD and GSH), and a decrease in lipid metabolites (MDA) to counteract oxidative stress damage." (PMID 38116381, 2023). "It has been reported that statins may play an important role in slowing the progression of liver fibrosis in patients with T2DM because statins can reduce hepatic expression of tumor necrosis factor-α (TNF-α), interleukin 6 (IL-6) and transforming growth factor-β (TGF-β)." (PMID 36899407, 2023). "CCl4 treatment could up‐regulate the pro‐inflammatory cytokines TNF‐α, IL‐6 and IL‐1β in the liver, and MulA treatment significantly reduced the levels of these cytokines, indicating that MulA might alleviate liver fibrosis via inhibiting inflammatory cytokines secretion." (PMID 37324833, 2023). "Furthermore, oxidative stress can, directly and indirectly, contribute to the up-regulation of the nuclear factor kappa-light-chain-enhancer of activated B cells (NF-kB) and pro-inflammatory cytokines (TNF-α, IL-6, and IL-1) that are involved in the apoptosis and development of hepatic fibrosis." (PMID 37242133, 2023). "Moreover, Antrodin C may inhibits liver fibrosis by other Signaling pathways like TNF-α-NF-κB, AMPK, and β-Catenin Signaling pathway." (PMID 35242813, 2022).
liver fibrosis (continued). "Furthermore, FFAs in the liver promote lipid peroxidation, the generation of highly reactive oxygen species, and the release of proinflammatory cytokines such as the tumor necrosis factor-α, which promotes inflammatory processes and liver fibrosis (steatohepatitis)." (PMID 36557281, 2022). "During age-related liver fibrosis, it is worth noting that necroptosis contributes to an increase in the number of proinflammatory M1 macrophages and expression of proinflammatory cytokines (TNF-α, IL-6, and IL-1β), as well as total collagen content in aging livers." (PMID 36110858, 2022). "Therefore, given that we detected increases in hepatic steatosis and expression of inflammatory cytokines, including TNF-α, in the EtOH-cohorts, we next assessed liver fibrosis by using both IHC for the fibrogenic marker α-smooth muscle actin (α-SMA) and Masson’s trichrome staining for collagen." (PMID 33815111, 2021). "Thus, it appears that etanercept does not exert positive effect on skeletal muscle indirectly through therapeutic effect on liver fibrosis, rather it prevents muscle wasting directly by inhibiting TNFα signalling in skeletal muscle where TNFα is acting as an atrophy-inducing factor." (PMID 33414474, 2021). "Furthermore, IL-4 as well as IL-13 could potently induce liver fibrosis which inhibited liver injuries due to accumulated Th1 like responses (such as TNF-α and IFN-γ) at the early stages of helminthic infection." (PMID 33489026, 2020). "Likewise, we noted a dampening of inflammation (a regular accompaniment of hepatic fibrosis) by antiplatelet drugs, reflected in diminished expression of TNF-α, and normalized levels of various markers (ALT, AST, albumin, and total bilirubin) signaling preservation of hepatic function." (PMID 33381477, 2020). "Genistein protected against liver fibrosis caused by S. japonicum and decreased the extent of hepatic granuloma via inhibiting activation of NF-κB signaling pathway and led to downregulation of inflammatory cytokines MCP1, TNFα, IL1β, IL4, IL10 in infected mice." (PMID 32410640, 2020). "For example, a study reported that CUR (200 mg/kg) could alleviate liver fibrosis in male rats by inhibiting the expression of inflammatory cytokines such as TNF-α, IL-6, and MCP-1 and eventually prevent the development and progression of obesity-related diseases." (PMID 33584555, 2020). "Thus, blocking TNF-α-driven inflammation at the appropriate stage of liver fibrosis could be an efficient strategy to prevent fibrosis." (PMID 31847135, 2019). "While it has been previously reported that Th1 immune responses are associated with acute infection, studies are now suggesting that Th1 cytokines such as IFN-γ and TNF-α could be involved in regulating hepatic fibrosis observed in chronic schistosomiasis disease." (PMID 29610679, 2018). "In addition, several IL-13 antibodies such as lebrikizumab, tralokinumab and QAX576 as well as the anti-TNF antibody etanercept and the immunomodulatory drug thalidomide are currently being evaluated for their anti-fibrotic potency in liver fibrosis and pulmonary fibrosis." (PMID 24678903, 2014). "Thus, TNF-α has been thought to be crucial for liver injury and subsequent liver fibrosis." (PMID 23755201, 2013). "Therefore, TNF-α and IL-6 secretion inhibition was considered to be able to reduce liver fibrosis." (PMID 23843869, 2013). "However, excessive and uncontrolled production of TNF-α may lead to systemic chronic inflammation, induction of hepatic apoptosis, and increased liver fibrosis." (PMID 20209097, 2010). "In a severe liver fibrosis model, treatment with cRLN2 not only effectively alleviated fibrosis but also restored the normal levels of inflammatory cytokine in serum (IFN-α, TNF-α, and IL-6)." (PMID 41552388, 2026).
liver fibrosis (continued). "PAE was found to inhibit hepatic fibrosis by reducing activated HSC proliferation, migration, and the expression of collagen fiber genes COL1 and α-Sma, as well as inflammatory markers TNFα and IL-6, and EMT markers (ECA, NCA, Vim, Snail)." (PMID 40103586, 2025). "This study demonstrated that daily oral treatment with sotagliflozin markedly upregulated antioxidant markers such as SIRT1 and Nrf2, attenuated TNF‐α, and reduced apoptotic and fibrogenic markers, thereby protecting against TAA‐induced liver fibrosis." (PMID 41498016, 2025). "In a 12-wk trial, a low-free sugar diet significantly reduced hepatic fibrosis, CRP, and TNF-α in MASLD." (PMID 39842721, 2025). "During liver fibrosis, IL-10 mitigates fibrosis by suppressing inflammatory cellular immune responses and the production of TGF-β1, TNF-α, and tissue inhibitors of metalloproteinases." (PMID 39995661, 2025). "Our findings suggest that TNF, IL-6, PPARG, and MMP9 are potential therapeutic targets that influence liver fibrosis progression by regulating inflammatory responses and apoptosis through multiple pathways." (PMID 39869574, 2025). "Among the various cytokines involved in liver fibrosis, TGF-β and TNF-α play crucial roles in its pathogenesis." (PMID 40575377, 2025). "By blocking the NF-κB signaling pathway, liver tissue can exhibit reduced expression of proinflammatory cytokines (IL-6 and TNF-α), in addition to decreased collagen deposition, fibrosis marker α-SMA expression, and liver fibrosis." (PMID 40552161, 2025). "This study aims to identify potential herbal drugs with anti-fibrotic activity by targeting multiple pathways involved in liver fibrosis, particularly focusing on the Tumour growth factor-beta (TGF-β) and tumor necrosis factor-alpha (TNF-α) proteins." (PMID 40575377, 2025). "Evidence shows that activated Kupffer cells can worsen liver injury by activating TGF-β and TNF signaling, leading to the production of new extracellular matrix (ECM) proteins like collagen, which contribute to liver fibrosis." (PMID 39182075, 2024). "Consistent with animal experiments, hepatic fibrosis markers (α-SMA, collagen I, and CTGF) and inflammatory markers (IL-1β, IL-6, and TNF-α) were significantly decreased in activated LX-2 cells after PFD and/or AGP treatment." (PMID 38946862, 2024). "In addition, eight studies reported the TNF-α level in liver fibrosis models, and the results demonstrated that treatment with curcumin could significantly reduce the TNF-α level compared to that in the liver fibrosis model group [n = 132, SMD = −4.57, 95% CI (−6.38, −2.76), p < 0.0001]." (PMID 38313314, 2024). "Another study demonstrated that oral administration of Lactobacillus paracasei N1115 alleviates HFD-induced hepatic steatosis and the release of the inflammatory factor tumor necrosis factor (TNF-α), thereby slowing down the progression of liver fibrosis." (PMID 38666855, 2024). "Th17 cells drive liver fibrosis in schistosomiasis by secreting IL-17, which activates TGF-β signaling and collagen deposition, along with TNF-α and IL-1β that boost hepatic stellate cell activation." (PMID 39700261, 2024). "The main indicators for evaluating the degree of hepatic fibrosis include HA, LN, Collagen I, Collagen III, PCIII, PIIINP, IV-C, IL-6, and TNF-α, α-SMA, HYP, PDGF-BB, CTGF and TGF-β1." (PMID 38781262, 2024). "The ethanol extracts of aerial parts exhibited potent hepatoprotective effects by significantly suppressing TNF-α and IL-6 levels in thioacetamide (TAA)-induced liver fibrosis in rats, thus restoring liver function." (PMID 38310564, 2024). "Some studies have further confirmed that KCs depletion can not only inhibit the production of IL-1β and TNF-α but also inhibit the activation of HSC, thereby alleviating liver fibrosis in a bile duct ligation (BDL)-induced liver fibrosis mouse model." (PMID 39635524, 2024).